OLIG2 (oligodendrocyte transcription factor 2)
Diseases named in the same sentence as OLIG2 in open-access papers (continued):
Sharing a sentence is not in itself a finding about the gene and the disease.
glioma (continued). "In spite this tendency of glioma stem cells to exhibit a proneural signature, some glioma stem lines preferentially express mesenchymal markers: the mesenchymal stem cell lines are CD44+, exhibit low CD15 and OLIG2 expression and are characterized by a high radioresistance." (PMID 30279357, 2018). "Glioma CSCs may produce VEGF, promoting vessel growth, while endothelial cells cocultured with glioma CSCs, facilitated the CSC-like phenotype of glioma cells by increasing the expression of Sox2, Olig2 and Bmi1." (PMID 30510501, 2018). "The transfected glioma cells grown in differentiated (DMEM with 10% FBS allows to maintain mixture of cells with various lineage) and stem cell conditions (NSA media supplemented with N2, B27, EGFFR and FGF) were stained using CD133, NESTIN, GFAP and OLIG2 markers." (PMID 27517625, 2017). "To determine the expression of CMV in the various glioma specimens, we stained primary GBM specimens with CD11B (a marker of blood cells and macrophages), CD45 (a marker of hematopoietic cells), antibodies against CMV gB glycoprotein and Olig2 (stem cell markers)." (PMID 27517625, 2017). "The functions of Id4, OLIG1, and OLIG2 during normal development, and our data suggest that Id4 and potentially other proteins such as FABP7 and PTPRZ1 might account for the formation of distinct glioma subtypes during oncogenic progression." (PMID 16018821, 2005). "Indeed, POU3F2, SOX2, SALL2, and OLIG2 have been shown to be the core set of transcription factors essential for GBM propagation, which are within the set of 19 transcription factors (including SOX1) required for successful reprogramming of differentiated glioma cells into GSCs48." (PMID 28425506, 2017). "Negative staining for markers like OLIG-2 and STAT6 further helps rule out other glial tumors such as oligodendrogliomas or other neuronal tumors, confirming the glial origin of the tumor and supporting the diagnosis of ependymoma." (PMID 41522411, 2025). "Therefore, Olig2 may not be a specific marker for a distinct type of glioma." (PMID 37274223, 2023). "Tumors stained mostly negative for glial histological markers commonly used for gliomas, such as GFAP and Olig2." (PMID 36869047, 2023). "Consistent with this trend, cell lines that did not express OLIG2, including HEK293 cells and U87-MG glioma cells were not suppressed by CT-179." (PMID 37333134, 2023). "Pediatric non-cycling PROM1+ cells were further classified according to the expression of other putative glioma stem cells marker such as SOX2 and OLIG2: 54% expressed both markers, 32% only SOX2, 6% only OLIG2, and 8% neither (right)." (PMID 35970913, 2022). "We found that the glioma tissue was diffusively positive for GFAP, Nestin, slightly positive for Olig2, S-100; the positive rate of Ki-67 was 65% and negative for Vimentin." (PMID 33391433, 2021). "We found that the delivery of CMV70-3P inhibitor significantly inhibited SOX2 expression in U118CMV infected and GBM13 glioma stem cells (p < 0.029 and 0.008) without altering the expressions of CD133, NESTIN and OLIG2." (PMID 27517625, 2017). "The majority of C6 glioma cells strongly expressed nestin and oligodendrocyte precursor cell markers such as PDGFR-α, NG-2, and Olig2, but not the neuron-specific marker Tuj1." (PMID 29161257, 2017). "Across the range of neural tumors, GFAP, OLIG-2 and MAP-2 are generally expressed by gliomas, while the neuronal marker synaptophysin is not." (PMID 25955030, 2015). "There are also limitations: Although GFAP is a robust glioma marker, it does not label all glioma subpopulations (e.g., GFAP-negative tumor cells), and future work could incorporate additional markers (e.g., Sox2, Olig2)." (PMID 41226489, 2025).
glioma (continued). "It has been proposed that glioma CSCs express differentiation markers similar to those in normal glia and neurons, such as of oligodendrocytes (ASCL1, OLIG2 and DLL3), astrocytes (GFAP), neurons (β-tubulin III, SYT1 and SLC12A5), and markers of inflamed astroglial cells (SERPINE1, TGFB1 and RELB)." (PMID 31661894, 2019).
glioblastoma (94 papers, 2010 to 2026). The most malignant astrocytic tumor (WHO grade IV). "This pattern aligns with Olig2’s role as a key transcription factor associated with glioblastoma stem-like cells." (PMID 40282990, 2025). "We found that ARNT2 knockdown decreased the expression of SOX9, POU3F2 and OLIG2, transcription factors implicated in glioblastoma cell tumorigenicity, and repressed glioblastoma stem-like cell tumorigenic properties in vivo." (PMID 29149419, 2018). "To further elucidate the association between LDH subunits and glioblastoma (GBM) phenotypes, we analyzed the expression of OLIG2 (a marker for the proneural phenotype) and VIM (a marker for the mesenchymal phenotype)." (PMID 39895794, 2025). "ASCL1 and OLIG2 are two basic-helix-loop-helix transcription factors that are highly co-expressed in glioblastoma (GBM)." (PMID 39609428, 2024). "Our results are consistent with most of current studies, as a significant proportion of WHO grade 4 tumors are predominantly glioblastomas, and it is therefore important to emphasize the prognostic value of Olig2." (PMID 38418976, 2024). "Histopathological staining demonstrated a higher fraction of OLIG2-positive tumor cells in high-neural glioblastoma samples but comparable sparse infiltration of NeuN+ cells within the tumor samples." (PMID 38760585, 2024). "In neurosphere assays of human glioblastoma cell lines, silencing METTL3 reduces the expression of glioblastoma reprogramming factors POU3F2, SOX2, SALL2, and OLIG2, and inhibits glioblastoma cell proliferation." (PMID 39473440, 2024). "On the tissue level, PIWIL1 expression was associated with a stem cell gene signature in non-small cell lung cancer, and expression of the stem cell markers POU5F1 (Oct3/4) and SOX2 and OLIG2 in colorectal cancer and glioblastoma, respectively." (PMID 38303021, 2024). "In brain tumors, the anti-differentiation function of OLIG2 plays an important role in tumor progression, as seen in glioblastoma (GBM) and in SHH MB." (PMID 37333134, 2023). "Meanwhile, astrocyte-like glioblastomas (Olig2-) extend in a collective-cell way, disrupting the BBB and causing marked inflammation and edema." (PMID 35740307, 2022). "According to the Ivy Glioblastoma Atlas, an anatomically annotated transcriptional dataset of human glioblastoma tumors, Olig2 expression is increased in areas of infiltrating tumor and cellular tumor, and reduced in areas of necrosis and around blood vessels." (PMID 35494072, 2022). "In view of the fact that the Olig2-Wnt7a signaling axis induces individual-cell co-option, it has been suggested that oligodendrocyte-like glioblastomas (Olig2+) spread in a subtle, single-cell form and preserve the BBB." (PMID 35740307, 2022). "Pediatric glioblastomas have the highest ratio of Olig2 occurrence, which are Ki-67 positive (mean 16.3%)." (PMID 33669639, 2021). "In line with its neural and stem cell renewal function, SALL2, combined with SOX2, POU3F2, and OLIG2 transcription factors, promotes the de-differentiation of glioblastoma cells into stem-like tumor propagating cells." (PMID 33692826, 2021). "Four core transcription factors (POU3F2, SOX2, SALL2, and OLIG2) are reported to be essential for glioblastoma propagation and sufficient to fully reprogram differentiated glioblastoma cells into glioblastoma stem cells." (PMID 31375149, 2019). "A combination of the transcriptional regulators Sox2, Olig2 and Zeb1 is robustly expressed in genetically diverse glioblastomas and is sufficient to transform astrocytes that have lost tumour suppressor gene pathways." (PMID 29759978, 2018). "OLIG2 is a basic helix-loop-helix (bHLH) TF that is critical in tumorigenesis and regulates the survival and expansion of glioblastoma (GBM)." (PMID 26517684, 2017).
glioblastoma (continued). "In an attempt to classify glioblastoma tumors into proneural and mesenchymal subtypes, we performed IHC on 38 glioblastoma samples with markers such as OLIG2, PDGFR-α for the proneural and CD44, YKL-40 for the mesenchymal subtype." (PMID 28744448, 2017). "By analyzing regions of YKL-40/OLIG2 expression, we preclassified glioblastoma tumors into proneural and mesenchymal glioblastoma subtypes (35/38; segregation efficacy 92.0%)." (PMID 28744448, 2017). "Proneural glioblastoma tumors contained more OLIG2-positive regions as expected (36.0 vs 83.4, ****p < 0.0001)." (PMID 28744448, 2017). "Conversely, tumors with weak YKL-40 positivity and strong OLIG2 sensitivity were categorized as proneural glioblastoma (n = 15)." (PMID 28744448, 2017). "The glioblastomas that arose from the GEMM showed a wide range of Olig2 staining intensities, which we graded from a scale of 0 to 3+." (PMID 27056901, 2016). "We characterized Olig2 staining intensity, an established biomarker for proneural glioblastoma, for each tumor." (PMID 27056901, 2016). "POU3F2 and other neuro-developmental transcription factors (SOX2, SALL2 and OLIG2) coordinate to play essential roles in the progression of glioblastoma." (PMID 27271588, 2016). "OLIG2, a neurodevelopmental transcription factor, is crucial for neural development and plays a key role in driving a transcriptional program that sustains the proliferation of glioblastoma stem cells." (PMID 40282990, 2025). "OLIG2 is frequently highly expressed in grade 4 glioblastoma as well." (PMID 41009560, 2025). "Many previous studies have reported the important role played by Olig2 in glioblastoma cell reprogramming, genotoxic resistance, and tumor phenotypic plasticity, which may be closely related to the underlying mechanisms of tumor growth." (PMID 38418976, 2024). "Finally, PIWIL1 knockdown in glioblastoma decreased the expression of neural stem and progenitor cell markers OLIG2 and Nestin." (PMID 38303021, 2024). "In three of our cases, necrosis or microvascular proliferation was present; these histologic features are not unique to glioblastomas but can be used as clues in such diagnostic scenarios in addition to Olig2." (PMID 38201659, 2024). "Furthermore, KLHDC8A expression positively correlated with the expression of SOX2 and OLIG2 in glioblastoma patients from TCGA and CGGA databases." (PMID 36394953, 2023). "Oligodendrocyte precursors (OPCs), expressing oligodendrocyte transcription factor 2 (Olig2), can serve as tumor progenitors in glioblastoma and may be actively involved in white matter vascularization." (PMID 35740307, 2022). "It is also in combination with POU3F2, SALL2, and OLIG2, able to induce glioblastoma tumor growth." (PMID 34021259, 2021). "Our study indicates a 22% expression of Olig2 in glioblastoma multiforme cohort." (PMID 33669639, 2021). "Prior to that, Olig2 was identified as a significant marker for glioblastoma stem cells (GSC)." (PMID 32160197, 2020). "Moreover, its expression is a recognized marker of the proneural subtype of glioblastomas and, even more importantly, in cooperation with Sox2, Pou3f2 and Sall2, Olig2 is a key master transcription factor of glioblastoma-initiating cells." (PMID 32316617, 2020). "In cancer stem cells, by the induction of a core set of neurodevelopmental transcription factors (POU3F2, SOX2, SALL2, and OLIG2) that are essential for glioblastoma propagation, differentiated glioblastoma cells can be fully reprogrammed into induced stem-like tumor-propagating cells." (PMID 31375149, 2019). "To ascertain the functional relevance of this association, we focused on three transcription factors members of this stem signature SOX9, POU3F2 and OLIG2, since the knockdown of these factors has previously been reported to inhibit glioblastoma cell tumorigenicity in vivo." (PMID 29149419, 2018). "Moreover, 88% of Ki 67 positive cells were Olig2 positive in pediatric glioblastoma." (PMID 33669639, 2021).
glioblastoma (continued). "Transcription factors like ASCL1, HES1, OLIG2, SOX2, and NOTCH-ligands (DLL1/3) play crucial roles in GBM plasticity by maintaining a pool of quiescent glioblastoma stem cells (GSCs)." (PMID 40358199, 2025). "ATRX, OLIG2, MGMT, and IDH2 were selected due to their critical roles in glioblastoma biology and prognosis." (PMID 40282990, 2025). "Key molecular players, such as ATRX, OLIG2, MGMT, and IDH2 proteins, contribute to critical oncogenic processes like chromatin remodelling, glioblastoma cell fate and de-differentiation, DNA repair and metabolic reprogramming." (PMID 40282990, 2025). "When CSCs derived from glioblastoma or CSC-depleted cultures of glioblastoma cells were exposed to low pH conditions, there was an upregulation of CSC markers such as OLIG2, OCT4, and NANOG." (PMID 39361163, 2024). "In glioblastoma stem cells (GSCs), for example, the expression levels of key stemness-related TFs (POU3F2, SOX2, SALL2, and OLIG2) are significantly higher than those in more differentiated tumor cells." (PMID 37370081, 2023). "Immunohistochemistry results indicated that GFAP, S-100, Olig-2, and ATRX were positive in more than 90% of glioblastomas." (PMID 37483487, 2023). "In our recent study evaluating the efficacy of osimertinib against EGFRvIII+ glioblastoma, we found that compared to D317, D10-0171 exhibited increased expression of growth-promoting GSC markers such as OLIG2, and resistance to growth inhibition by EGFR-TKIs." (PMID 35456993, 2022). "A recent study identified four transcription factors (SOX2, SALL2, OLIG2, and POU3F2) as the minimal core sufficient to reprogram differentiated glioblastoma (GBM) cells into stem-like cells." (PMID 34282187, 2021). "One of the possible reasons is the use of serum-free neurobasal medium in all the recent studies of 3D cell culture systems for glioblastoma, which enriches OPC-like phenotype upon enhanced Olig2 and Sox2 which are the markers for the same." (PMID 34489494, 2021). "ZEB1 promotes cancer stemness in glioblastoma, where it is part of an autoregulatory loop together with SOX2 and OLIG2, two transcription factors with well-established functions in neural stem/progenitor cells." (PMID 34433050, 2021). "In a study conducted on glioblastoma stem cells (GSCs), NOTCH1, SOX2, SALL2, POU3F and OLIG2 blocked differentiation in GSCs, confirming the observations made in GBM by Suvà and colleagues." (PMID 32634370, 2020). "We found that ARNT2 knockdown not only impaired the cell tumorigenicity in vivo but also resulted in decreased expression of SOX9, POU3F2 and OLIG2, hence placing ARNT2 at the core of transcriptional regulations of glioblastoma cell tumorigenicity." (PMID 29149419, 2018). "Glioblastoma stem cells rely on multiple key stemness-related proteins such as Nestin, CD133, SOX2, Olig2, BMI1, and ZEB138,39." (PMID 30022047, 2018). "A subset of only four of them–SOX2, OLIG2, POU3F2, and SALL2–was sufficient to fully reprogram differentiated cells into glioblastoma stem-like cells." (PMID 29773872, 2018). "Their expression in differentiated cells strongly correlated with the down-regulation of transcription factors like OLIG2, POU3F2, SALL2, SOX2, capable of reprogramming differentiated glioblastoma cells into stem-like cells." (PMID 29773872, 2018). "This technique allowed confirming the diagnosis of 8 cases of glioblastomas and reclassifying, within another group, 7 remaining cases which showed a positive immunostaining of both INA and OLIG-2 antibodies." (PMID 28785587, 2017). "We validated this MMS on human glioblastoma tissue sections with the use of immunohistochemistry on preclassified (YKL-40 high or mesenchymal glioblastoma and OLIG2 high or proneural glioblastoma) tumor samples (n = 30)." (PMID 28744448, 2017). "We found in our study in preclassified glioblastoma tumors and cells resides in ROH coexpressed both YKL-40 and OLIG2 proteins." (PMID 28744448, 2017).
glioblastoma (continued). "In this study, we categorized glioblastoma tumors on the basis of expression of YKL-40 and Olig2 using a novel algorithm for semiquantitative scoring of “tumor regions” that were stained for each of these markers." (PMID 28744448, 2017). "We herein found that expression of SOX2 was decreased, whereas expression of OLIG2 and POU3F2 were increased in both rat and human glioblastoma cell lines under sphere culture conditions." (PMID 28717188, 2017). "Our data indicate that critical stem cell regulators, such as SOX2 and OLIG2, are induced by the ZEB1-miR-200 feedback loop in glioblastoma." (PMID 23818228, 2013). "The tumor displayed pathologic features initially suggestive of glioblastoma, including diffuse but atypical glial fibrillary acidic protein (GFAP) expression, positive but weak oligodendrocyte transcription factor 2 (Olig2) staining, high mitotic activity, and pseudopalisading necrosis." (PMID 42211592, 2026). "For example, in glioblastoma, ARNT2 has been shown to be highly expressed in proliferative subpopulations and to promote tumorigenicity through the regulation of key transcription factors such as SOX9, POU3F2 (BRN2), and OLIG2." (PMID 40723431, 2025). "Other immunohistochemistry markers usually considered and analyzed for glioblastoma are Glial Fibrillary Axonal Protein (GFAP), S-100, vimentin, oligodendrocyte transcription factor 2 (Olig2) and ATRX, with some finding at least one positive marker in more than 90% of glioblastomas." (PMID 39518074, 2024). "In glioblastomas, cycle-dependent kinase 5 (CDK5) phosphorylates DRP1 at Ser616 and increases mitochondrial cleavage, which then induces the expression of stemness genes (OLIG2, OCT4, NANOG, NESTIN, POU3F2, CD133, SSEA1)." (PMID 37370081, 2023). "Here SWIM implicated FOSL1 as a putative master regulator of a core of four master neurodevelopmental transcription factors (i.e., SOX2, SALL2, OLIG2, POU3F2), whose induction was demonstrated to be sufficient to reprogram fully differentiated glioblastoma cells into stem-like cells." (PMID 33785068, 2021). "Moreover, imidazoline derivatives were identified as potent oligodendrocyte lineage transcription factor 2 (OLIG2) inhibitors, promising agents in the treatment of glioblastoma tumors." (PMID 33327611, 2020). "The inhibition of switch genes highly correlates with the activation of genes related to neural development and differentiation, such as the 4-core OLIG2, POU3F2, SALL2, SOX2, whose induction has been shown to be sufficient to reprogram differentiated glioblastoma into stem-like cells." (PMID 30497369, 2018). "A more recent study has shown that the tumor-propagating potential of glioblastoma cells can be enhanced by increasing the expression of a set of transcription factors normally involved in neuronal development, including POU3F2, SOX2, SALL2 and OLIG2." (PMID 29609590, 2018). "This, in combination with analysis of glioblastoma formalin-fixed paraffin-embedded tissue samples identified a nine-gene signature including IGFBP-2, chitinase-3-like protein 1 (CHI3L1)/YKL-40, galectin 3 (LGALS3) and OLIG2 that was predictive of worse clinical outcomes." (PMID 40429889, 2025). "In glioblastoma multiforme (GBM), a core set of neuro-developmental TFs (POU3F2, SOX2, SALL2, OLIG2) has been identified that was sufficient to reprogram differentiated glioblastoma cells to CSCs." (PMID 33297508, 2020). "Thus, Prrc2a “reading” of OLIG2 mRNA (and its demethylation by FTO) might be relevant in the context of glioblastoma too." (PMID 32316617, 2020). "Indeed, exposure of glioblastoma stem-like cells to recombinant BMP7 in vitro increased SMAD1/5/8 phosphorylation, inhibited cell proliferation, stimulated glioblastoma differentiation, decreased neurosphere formation and attenuated expression of the stem-like genes Nanog, SOX2, Nestin and Olig2." (PMID 29799477, 2018).